SIRT1 (sirtuin 1)
Diseases named in the same sentence as SIRT1 in open-access papers (continued):
Sharing a sentence is not in itself a finding about the gene and the disease.
colitis (continued). "The mRNA levels of Sirt1 and Sirt3 were not significantly changed in each tissue after colitis induction." (PMID 38415949, 2024). "detected insignificant SIRT1 RNA and protein expression in the lamina propria mononuclear cells from patients with IBD and observed that SIRT1 downregulation promoted the sustained production of inflammatory cytokines and oxidative stress in colitis." (PMID 37483618, 2023). "Hence, the current study was designed to investigate the potential involvement of the antioxidant/cytoprotective SIRT1/FoxO3a/Nrf2 axis and the pro-inflammatory PI3K/AKT pathway in the ameliorative effects of REB against AA-evoked colitis in rats." (PMID 37111290, 2023). "Experimental evidence has shown that reducing NAD+ and SIRT1 levels in the colon of mice, using the olefin receptor agonist norisopodine (which expands epigenetic Treg cells as an aryl hydrocarbon receptor agonist), alleviates DSS-induced colitis." (PMID 37371959, 2023). "We observed that the expression of SIRT1, known as a master metabolic regulator, was significantly decreased in several tissues including the liver, SAT, BAT, and colon of DSS-induced colitis mice compared to non-colitis control mice." (PMID 33674694, 2021). "HE ameliorated colitis in prophylactic in HFD mice and it was, at least partly, due to the restoration of the gut integrity, suppression of inflammation and apoptosis via modulation of colonic Sirt1, RAGE and DDOST signaling." (PMID 34380504, 2021). "Additionally, SIRT1, a key player in cellular metabolism and stress response, interacts with the STAT3 signaling cascade, thereby modulating the inflammatory response in colitis." (PMID 40672369, 2025). "This, in addition to the inhibitory effect of TLR4 on SIRT1 levels and its proven role in ROS production, supports the hypothesis that TLR4/NF-κB/NLRP3 inflammasome signaling is the keystone in the inflammatory events encountered in DSS-induced colitis." (PMID 35631426, 2022). "Finally, the correlation between NOR-mediated activation of AhR, repression of glycolysis, regulation of NAD+/SIRT1/SUV39H1/H3K9me3 signals, induction of Treg cells, and remission of colitis was confirmed in mice with DSS-induced colitis by using CH223191 and HK2 plasmid." (PMID 29449535, 2018). "NOR promoted Treg differentiation and reduced colitis by targeting glycolysis and the subsequent NAD/SIRT1/SUV39H1/H3K9me3 signaling pathway." (PMID 37483618, 2023). "Then, the causal link between activation of AhR, reduction of glycolysis, regulation of NAD+/SIRT1/SUV39H1/H3K9me3 signals, induction of Treg cells, and alleviation of colitis by NOR was confirmed in mice with colitis." (PMID 29449535, 2018). "The correlation between activation of AhR, repression of glycolysis, regulation of NAD+/SIRT1/SUV39H1/H3K9me3 signals, induction of Treg cells, and eventual anti-colitis effect of NOR were validated by using CH223191 and HK2 plasmid." (PMID 29449535, 2018). "The results showed that GW9662 itself did not affect the disease symptoms of mice with colitis, but significantly weakened bergenin-mediated regulation of levels of IL-6, TNF-α, acetylated NF-κB-p65, SIRT1 and nuclear translocation of NF-κB-p65 in colons, and consequent anti-colitis effect." (PMID 29375382, 2017).
Anxiety (67 papers, 2012 to 2026). Intense feelings of nervousness, tension, or panic often arise in response to interpersonal stresses. "SIRT1, 2, 3, and 5 are the most widely implicated in psychiatric illnesses, including roles in substance use, longevity, mood, anxiety, and psychotic illnesses." (PMID 39404407, 2024). "Receiver-operating characteristic (ROC) analysis confirmed that plasma SIRT1 levels had good diagnostic accuracy for PD with anxiety and EDS." (PMID 37718350, 2024). "Typically, activation of the SIRT1/NHLH2/MAO-A pathway is associated with increased anxiety behavior." (PMID 39595020, 2024). "Human studies, though unbiased, seem to demonstrate the association of SIRT1 with anxiety states and several psychiatric disorders." (PMID 37373917, 2023). "As for the relationship between Sirt1 and NF-κB, studies demonstrated that anxiety-like behavior caused by brain hypoxia can be suppressed by Sirt1 via the NF-κB pathway." (PMID 35401226, 2022). "Current studies indicated that EDA attenuated CSDS-evoked depressive symptoms and CSDS-induced anxiety behaviors, and the underlying mechanisms were associated with the alteration of expression of Sirt1/Nrf2/HO-1/Gpx4 pathway in the Hip." (PMID 35130906, 2022). "One Chinese case-control study, which included 259 patients with PD and 253 healthy controls, demonstrated that the SIRT1 rs7895833?GG mutant genotype was associated with more severe anxiety symptoms (assessed using the Hamilton Anxiety Scale)." (PMID 33269110, 2020). "Taken together, the effects of VitD3 and Res on improving ET-associated anxiety-like behavior could involve the activation of the anti-inflammatory and Sirt1 pathways." (PMID 38684734, 2024). "LPS-induced anxiety is linked to reduced SIRT1 and increased IL-1." (PMID 39275174, 2024). "The authors hypothesize that sustained and hyperactivated SIRT1 causes compulsive hyperactivity, the need for excessive exercise, and anxiety, which leads to further self-determination and increased activation of SIRT1." (PMID 37373917, 2023). "Moreover, SIRT1 has been implicated in regulating anxiety, depressive and exploratory behaviors, and the behaviors associated with drug abuse in the VTA and NAc." (PMID 32922581, 2020). "SIRT1 polymorphism frequencies were investigated in individuals with psychiatric disorders and controls; both rare and common alleles were associated with a higher risk of anxiety." (PMID 30416425, 2018). "Finally, these findings are now being investigated in human populations, Libert and colleagues for example showed that rare human SIRT1 variants are associated with anxiety and mood disorders." (PMID 28194114, 2017). "So far, genetic variations in SIRT1 have been associated with depressive and anxiety disorders." (PMID 26509718, 2015). "Behavioral tests revealed that SIRT1 knockdown rescued morphine-induced memory impairment and anxiety-like behaviors, while overexpression exacerbated these effects." (PMID 40621197, 2025). "The neuroprotective effect of RES via the SIRT1/AMPK/BDNF pathway contributes significantly to improved anxiety behavior." (PMID 39275174, 2024). "The Anshen Dingzhi prescription, from the Qing Dynasty’s “Yi Xue Xin Wu” (1732 CE), improves anxiety by activating the SIRT1-PGC-1α pathway, mitigating mitochondrial dysfunction." (PMID 39275174, 2024). "It follows then that direct inhibition of SIRT1 within the area of memory formation in the hippocampus produces anxiety." (PMID 39404407, 2024). "In mice subjected to the CUMS paradigm, RES treatment reversed anxiety-like behavior and improved mitochondrial dysfunction via the SIRT1/PGC1α/SIRT3 pathway." (PMID 39275174, 2024). "The study found that maternal separation from their children increased anxiety and sadness, pro-inflammatory cytokines, and suppressed the activity of the NF-κB/Sirt1 signaling pathway in male offspring." (PMID 38385077, 2024).
Anxiety (continued). "Dysfunction in the SIRT1-PGC-1α mitochondrial pathway is associated with fear generalization and anxiety-like behavior triggered by SPS." (PMID 39275174, 2024). "Stress-induced SIRT1 expression in the NAc regulates anxiety behaviors, and SIRT1 antagonists reduce these behaviors." (PMID 39275174, 2024). "Glucocorticoid signaling in the brain increases MAO-A mRNA levels, with SIRT1/NHLH2/ MAO-A pathways driving anxiety-like behavior." (PMID 39275174, 2024). "The amygdala, a key brain region for anxiety, shows increased SIRT1 levels in response to caloric restriction, implicating this sirtuin in anxiety modulation." (PMID 39275174, 2024). "It is established that circadian rhythms and sleep play a role in mood and anxiety stability; this study highlights a role for SIRT1 in linking these two." (PMID 39404407, 2024). "Specifically, NHLH2 is hypoacetylated in SIRT1 OX mice compared to wild-type, highlighting SIRT1’s role in anxiety." (PMID 39275174, 2024). "Overexpression of N-acetyltransferase in the hippocampus correlates with anxiety-like behavior and higher SIRT1 levels, but conflicting reports exist regarding hippocampal SIRT1 expression." (PMID 39275174, 2024). "Within the basal nucleus of the stria terminalis, for example, SIRT1 overexpression decreased anxiety behaviors through normalization of the corticotropin-releasing hormone." (PMID 39404407, 2024). "In single prolonged stress (SPS) mice mimicking post-traumatic stress disorder (PTSD), Sirt1 deleted mice had less anxiety and freezing time, which indicated SIRT1 as a potential therapeutic target for PTSD." (PMID 34650436, 2021). "Sustained, hyper-activated SIRT1 results in compulsive hyperactivity, need to over-exercise, and anxiety, all of which lead to further self-starvation, and increased activation of SIRT1." (PMID 32499508, 2020). "MAO-A inhibitors have been reported to normalise anxiety differences in murine models exhibiting altered brain SIRT1 levels." (PMID 32423100, 2020). "The search for direct targets of miR-138 lead us to focus on Sirt1, known to play a role in modulating Aβ and importantly, behavior such memory and anxiety in mice." (PMID 33519353, 2020). "The downregulation of Sirt1 is consistent the literature showing its effects on Aβ, memory, and anxiety." (PMID 33519353, 2020). "We finally observed that Sirt1, a direct target of miR-138 involved in Aβ production, learning and memory as well as anxiety, is decreased following miR-138 overexpression." (PMID 33519353, 2020). "It is expected that increased SIRT1 activity induced by acute stress would decrease glutamatergic transmission in the dentate gyrus and modulate anxiety behavior, functioning as an adaptive role after an acute stress." (PMID 30271963, 2018). "This modulation of the behavioral response in the open field links the rapid effects of changes in SIRT1 activity that we observed in the slice preparation to modulation of anxiety behaviors mediated by changes in SIRT1 activity in the behaving animal." (PMID 30271963, 2018). "Brain-specific SIRT1-knockout mice have less anxiety-like behaviors and more exploratory drive than their wild-type (WT) littermates." (PMID 30416425, 2018). "Here, we demonstrate that SIRT1 activity rapidly modulates intrinsic and synaptic properties of the dentate gyrus granule cells and anxiety behaviors through deacetylation of BK channel α subunits in control animals." (PMID 30271963, 2018). "For example, increased Sirt1 levels in murine brains due to CR were shown to increase anxiety and decrease exploratory drive." (PMID 28194114, 2017). "The study also demonstrated that in mice SIRT1 increases anxiety by deacetylating the brain-specific helix-loop-helix transcription factor, nescient helix loop helix 2 (NHLH2), which increases its activity on the monoamine oxidase A (MAOA) promoter." (PMID 26509718, 2015).
Anxiety (continued). "By combining viral-mediated SIRT1 knockdown and overexpression with behavioral, ultrastructural, and molecular analyses, we demonstrate that SIRT1 activity in the BLA bidirectionally regulates morphine-associated memory persistence, synaptic plasticity, and anxiety-like behaviors." (PMID 40621197, 2025). "SIRT1 activity in hippocampal neurons mediated anxiety and depressive-like behaviors in mice." (PMID 41304625, 2025). "RES, as a SIRT1 agonist, can provoke anxiety-like behavior via restriction of food intake." (PMID 39275174, 2024). "The main molecular pathways supporting the anti-anxiety effects of RES treatment include the SIRT1/AMPK/CREB/BDNF pathway, which helps restore neurotransmitter balance, improve synaptic plasticity, increase mitochondrial biogenesis, and enhance glucose uptake by neuronal cells." (PMID 39335576, 2024). "The effects of VitD3 and Res may involve the activation of anti-inflammatory and Sirt1 pathways, leading to improvements in anxiety, memory, and motor coordination deficits observed in the ET model." (PMID 38684734, 2024). "SIRT1’s influence on behavior may be mediated by changes in serotonin and other neurotransmitter levels affecting anxiety." (PMID 39275174, 2024). "The antioxidant, anti-inflammatory, pro-neurogenic, and neuromodulatory properties of VitD3 could contribute to reductions in anxiety by modulating various pathways, including Sirt1 and neuroinflammation." (PMID 38684734, 2024). "It is found that increasing the expression of SIRT1 in male mouse BNST could ameliorate anxiety behaviors induced by chronic stress." (PMID 39698215, 2024). "However, this has been opposed in data from other specific brain regions where increases in SIRT1 lead to decreasing anxiety." (PMID 39404407, 2024). "Anorexia may arise from pathological positive feedback loops: voluntary food restriction activates SIRT1, promoting anxiety, hyperactivity, and addiction to starvation, exacerbating dieting and exercising, thus further activating SIRT1." (PMID 39275174, 2024). "Moreover, SIRT1 levels were increased directly in the NAc by the use of viral-mediated gene transfer, which resulted in an increase in depressive- and anxiety-like behaviors when mice were assessed in the open-field, elevated plus maze, and forced swim tests." (PMID 39275174, 2024). "Dysregulation of the apelin-SIRT1-NF-κB axis may lead to neuroinflammation and anxiety-like behavior." (PMID 39275174, 2024). "Our previous research results show that administration of BER to inhaled METH-addicted rats via modulation of neuroinflammation (NF-Κb, TLR4, Sirt1, and α-actin) improves anxiety-related behavior and decreases relapse (in the conditional place preference task)." (PMID 36594063, 2023). "SIRT1 knockout mice showed increased anxiety behavior and decreased activity." (PMID 38374960, 2023). "Similarly, an involvement of miR-132/212 in stress/anxiety-related behaviors as well as in the regulation of the levels of Sirt1 and PTEN have been also recently described." (PMID 37298523, 2023). "It has been shown that via activating the Sirt1/NF-κB pathway resveratrol could attenuate inflammatory responses and anxiety-like behaviors induced by chronic normobaric hypoxia in male C57BL/6 mice." (PMID 37273278, 2023). "Accordingly, we hypothesized that EDA might ameliorate depressive and anxiety-like behaviors via Sirt1/Nrf2/HO-1/Gpx4 pathway." (PMID 35130906, 2022). "Furthermore, quercetin acts as an antidepressant by targeting SIRT1 to reverse depressive and anxiety-like behaviors and hippocampal neuroinflammation." (PMID 35935939, 2022). "Moreover, reports have indicated that SIRT1 inhibitors reverse sleep deprivation (SD)-induced depressive and anxiety-like behaviors and hippocampal neuroinflammation." (PMID 35935939, 2022).
Anxiety (continued). "In addition, it was suggested that SIRT1 regulates anxiety by the de-acetylation of a transcription factor regulating the monoamine oxidase A gene in the brain, which is involved in oxidative deamination of dopamine, norepinephrine, and serotonin." (PMID 34867800, 2021). "Our results suggest that AN may arise from pathological positive feedback loops: voluntary food restriction activates SIRT1, promoting anxiety, hyperactivity, and addiction to starvation, exacerbating the dieting and exercising, thus further activating SIRT1." (PMID 32499508, 2020). "It has been reported that SIRT1 regulates anxiety and addictive behaviour, although the exact mechanism remains unclear." (PMID 32423100, 2020). "Additionally, SIRT1 has been reported to regulate anxiety, depressive and exploratory behaviors, and behaviors associated with drug abuse in the VTA and NAc." (PMID 32922581, 2020). "We went on to test the effects of SIRT1 manipulation on anxiety in a mildly stressful paradigm." (PMID 30271963, 2018). "Interestingly, loss of the ability of SIRT1 to affect the physiological conditions of dentate gyrus granule cells during chronic stress may contribute to the maladaptive processes that occur in response to repeated stressors and increased anxiety associated with responses to chronic stress." (PMID 30271963, 2018). "Indeed, our behavior results showed SIRT1 manipulation affects anxiety behavior during a mild stressor." (PMID 30271963, 2018). "Finally, we show that modulation of SIRT1 activity in the dentate gyrus can rapidly affect anxiety behavior in a BK channel-dependent manner." (PMID 30271963, 2018). "Various studies have identified detrimental phenotypes in knockout mice; for example, ATF5-KO mice may have abnormal cortical development and abnormal behaviors, such as anxiety, and SIRT1-KO mice may have abnormal bone development, autoimmune disease, and other problems." (PMID 38278820, 2024). "Notably, SIRT1 has a dual influence on stress-related anxiety behavior." (PMID 39335576, 2024). "Finally, several clinical and psychopathological conditions have not been investigated, such as mood state, hyperactivity, and presence of anxiety or physical activity, that could affect the immune system and SIRT1 of patients with AN." (PMID 37373917, 2023). "This study found that the daily rhythm of SIRT1 was significantly related to open field behavior in multiple tissues, suggesting that melatonin may regulate circadian clock by affecting SIRT1 mRNA, thereby affecting the daily rhythm patterns of anxiety behavior and exploratory behavior." (PMID 38374960, 2023). "Furthermore, in the hippocampus and amygdala of miR-132/212 conditional knockout and miR-132 transgenic mice, expression of sirtuin 1 (SIRT1) and phosphatase and tensin homolog (Pten), two miR-132 target genes implicated in the regulation of anxiety, was differentially regulated." (PMID 36979479, 2023). "Therefore, we speculated that EDA improved depressive and anxiety-like behaviors by activating the Sirt1/Nrf2/HO-1/Gpx4 signaling pathway." (PMID 35130906, 2022). "Suppression of SIRT1 is noteworthy in that elevated levels of activity enhance MAOA expression and accelerate serotonin turnover, promoting anxiety-like behaviors." (PMID 41515464, 2026). "Glucocorticoid signaling in different brain areas can increase MAO-A mRNA levels via the SIRT1/NHLH2/MAO-A pathway, promoting anxiety-like behavior." (PMID 39335576, 2024). "EX527 also alleviated fear conditioning and anxiety-like behaviors, linking PTSD-like symptoms to increased SIRT1 activity in the CA1 area." (PMID 39275174, 2024). "In a recent investigation reduced SIRT1 expression in the BNST and corticotropin-releasing factor (CRF) expression were observed in mice model anxiety induced by chronic stress exposure." (PMID 39698215, 2024).